UPF1 (UPF1 RNA helicase and ATPase)
Diseases named in the same sentence as UPF1 in open-access papers (continued):
Sharing a sentence is not in itself a finding about the gene and the disease.
tumor (continued). "We injected subcloned control and Upf1-targeted KPC cells into the tails of the pancreata of B6 albino mice (n = 10 mice per treatment) and monitored tumor growth and animal survival." (PMID 33404013, 2021). "Expression levels for NMD-related factors (UPF1, UPF2, UPF3A, UPF3B, SMG1, SMG2, SMG6, and SMG7) were calculated from microarray-derived datasets of primary tumor samples (n = 40 MSI, n = 48 MSS) and matched normal colon samples (n = 95)." (PMID 30228267, 2018). "UPF1 antibody staining was obviously weaker in the tumor areas than in the adjacent nonmalignant epithelia in most NPC biopsy samples." (PMID 41293174, 2025). "UPF1 and UPF2 were also gene edited in 4T1 and B16/F10 tumor." (PMID 36443756, 2022). "DHX8, EIF3G, RBM22, U2AF1 UPF1 and YBX-1 are also candidates therapeutic targets for cancer therapy because the tumor cell progression was strongly inhibited by the downregulation of these RBPs in cancer cells, including HCT116, SUIT2 and OE33 cells, but not in non-cancerous cells." (PMID 34202873, 2021). "These indicated that UPF1 was involved in HCC and might play an important role in tumor progression." (PMID 31040354, 2019). "IHC and real time PCR showed that UPF1 expression was decreased in HCC and might play an important role in tumor progression." (PMID 31040354, 2019). "Immunofluorescence analysis of skin SCC lesions versus surrounding unaffected skin showed that only expression of CSL but not UPF1, Ku70, and Ku80 were decreased in the SCC-associated fibroblasts." (PMID 31467287, 2019). "In conclusion, our results suggest that hypoxia-induced suppression of UPF1 expression decreases NMD efficiency, leading to the stabilization of COX-2 and PD-L1 mRNAs, thus activating the p38/MAPK and JAK2/STAT3 pathways and promoting tumor progression in NPC cells." (PMID 41293174, 2025). "Since the UPF1 expression level is critical for NMD activity, we hypothesized that the stabilization of NMD target genes as a consequence of impaired NMD in UPF1-KD cells might contribute to tumor progression." (PMID 41293174, 2025). "Further, we found that inhibition of UPF1 suppressed the malignant phenotype of ECSCs by destabilizing the oncogene LINC00963, which acted as an endogenous competition RNA (ceRNA) to prevent the tumor suppressor miR-508-5p from binding to the 3′UTR of SOX2 mRNA." (PMID 35318304, 2022). "Also, UPF1-overexpressing prostate cancer (PC3) cells injected as tumor explants in nude mice present no significant tumor growth." (PMID 33926465, 2021). "A negative effect of UPF1 and UPF2 expression on the host's anti-tumor response was observed (P<0.01)." (PMID 18612427, 2008).
cancer (39 papers, 2016 to 2026). A tumor composed of atypical neoplastic, often pleomorphic cells that invade other tissues. "In this line, the cancer-associated mutations in eRF1 can also disrupt its interactions (e.g., UPF1 and eRF3), further impairing translation termination and potentially contributing to tumorigenesis." (PMID 41189592, 2025). "The SMG1 kinase within the NMD machinery has a crucial role, and any alteration (cancer mutations) in it disrupts UPF1 phosphorylation, eventually resulting in improper functioning of NMD to detect mRNAs containing PTC." (PMID 41189592, 2025). "The results showed that compared with high expression of UPF1, low expression of UPF1 was associated with a poor prognosis in most cancers, including disease specific survival (DSS), overall survival (OS) and progression free interval (PFI)." (PMID 36421841, 2022). "Lastly, pan-cancer analysis revealed that UPF1 disorders were closely associated with various cancer outcomes." (PMID 36421841, 2022). "Up-frameshift mutant 1 (UPF1) is the core protein of the nonsense-mediated mRNA degradation pathway, which is tightly associated with the tumorigenesis and progression of many cancers, such as gastric, colorectal, and lung cancer." (PMID 35318304, 2022). "MiR‐210 in exosomes secreted by cancer‐associated fibroblasts promotes EMT by targeting UPF1 through PTEN/PI3K/AKT pathway in NSCLC cells." (PMID 33939301, 2021). "In this work, we investigated two alternatively-spliced UPF1 isoforms with different mRNA motifs, and we traced significant structural dynamics by inserting cancer-derived mutations in the UPF1 mRNA binding pocket." (PMID 34884553, 2021). "The cancer-associated UPF1 variants (P533L/T and A839T) resulted in decreased protein–mRNA binding efficiency." (PMID 34884553, 2021). "The significant structural changes upon inserting the most frequently occurring cancer mutations in the UPF1 isoform_1 bound with mRNA motifs were investigated." (PMID 34884553, 2021). "Altogether, our analysis of the structural changes in different UPF1 systems suggests the flexible nature of the substrate binding region in UPF1 with a predictable impact by certain cancer-associated mutations." (PMID 31718065, 2019). "In silico screening of UPF1 stability change as a function over 41 cancer mutations has identified five variants with significant effects: K164R, R253W, T499M, E637K, and E833K." (PMID 31718065, 2019). "The cancer genomic sequencing data has identified frequently mutated residues in the CH-domain and ATP-binding site of UPF1." (PMID 31718065, 2019). "This complicates the utility of using genetic mutation of UPF components from cancer genome sequencing as an argument for stratifying patients for trials with UPF1 drug leads." (PMID 31718065, 2019). "The recurrent cancer mutations analysis in the UPF1 gene using the cancer genome atlas (TCGA) sequencing data shows that 31 residues located in the UPF2 interacting domain (i.e., CH-domain) of UPF1 and 10 residues at the ATP-binding site/substrate pocket were found to be frequently mutated." (PMID 31718065, 2019). "For the current study, we chose a subset of cancer associated mutations in the UPF1 protein from the cancer genomics database cBioPortal, and selected mutations that are located in the ATP-binding site or CH-domain of UPF1." (PMID 31718065, 2019). "In this study, we set out to first determine whether the NMD pathway component UPF1 was in fact mutated to a degree in human cancers; and if so, what the effects of these mutations might be on the protein function." (PMID 31718065, 2019). "Finally, pan-cancer analysis showed that poor prognosis was associated with low expression of UPF1." (PMID 36421841, 2022). "LeuAAG-001-N-3p-68-85 was validated to target UPF1, a regulator of mRNA decay, while AlaAGC-002-N-3p-58-75 was linked to the suppression of ASCL2, a transcription factor involved in cancer progression." (PMID 40981380, 2025).
cancer (continued). "Such disruptions by cancer mutations can potentially inhibit UPF1 phosphorylation by the SMG1 kinase, compromising the NMD machinery’s ability to detect PTC-containing mRNAs and eventually leading to cancer progression." (PMID 41189592, 2025). "The upregulation and downregulation of UPF1 has been ascertained in numerous cancers, depending on their type." (PMID 36766761, 2023). "UPF1 is downregulated in numerous cancers, which correlates with poor prognosis and low overall survival (OS) rates." (PMID 36766761, 2023). "Pan-cancer cohorts in the TCGA datasets were divided into the high UPF1 group and low UPF1 group, according to the median value of UPF1 expression." (PMID 36421841, 2022). "Taken together, SNHG5 plays a critical role to promote HCC cell proliferation and cancer stem cell-like properties via UPF1 and Wnt/β-catenin pathway." (PMID 35338348, 2022). "In summary, this study basically confirmed that SNHG5 promotes HCC proliferation and cancer stem cell-like properties by regulating UPF1 to activate the Wnt-signaling pathway." (PMID 35338348, 2022). "The qRT-PCR results from 10 paired ccRCC samples collected from our Cancer Center showed that UPF1 expression was significantly lower in cancer tissues than in normal kidney tissues (p < 0.05)." (PMID 36421841, 2022). "Depletion of Linc-ASEN lncRNA or UPF1 increases the p21 mRNA level to mediate cellular senescence in cancer cells." (PMID 36552825, 2022). "It was found that UPF1 expression in cancer tissues was higher than that in adjacent normal tissues." (PMID 34520393, 2021). "These conflicting functions of UPF1 show that UPF1 is an essential molecule for monitoring the RNA quality of cancer cells." (PMID 34202873, 2021). "Western blotting showed that cyclin B1 was decreased by the downregulation of UPF1 in HCT116, SUIT-2 and OE33 cells, suggesting that abnormal cell division occurred in UPF1-downregulated cancer cells." (PMID 34202873, 2021). "The UPF1 residues interacting with AMPPNP as well as residues around 8 Å of AMPPNP were characterized and mutation association with different cancer types was considered." (PMID 31718065, 2019). "The cancer genomic sequencing data suggests that residues in the ATP-binding site and CH-domain (i.e., UPF2 interacting interface) of the UPF1 protein are frequently mutated, and we assessed the effects of those mutations on UPF1using in silico methodologies." (PMID 31718065, 2019). "In particular, the cancer-derived mutations within SMG1 located at 248–910 and 2200–2400 amino acids were evaluated in terms of the change in affinity or stability in the presence of SMG8/SMG9 and UPF1, respectively." (PMID 41189592, 2025). "Activation of the p38 MAPK and JAK2/STAT3 signaling pathways have both been reported to increase the expression level of COX-2 in cancers, suggesting that UPF1 might regulate COX-2 expression by activating the p38 MAPK and JAK2/STAT3 pathways." (PMID 41293174, 2025). "The role of the miRNA and lncRNA interplay with UPF1 in various types of cancer is pondered below." (PMID 36766761, 2023). "Finally, the co-expressed genes of UPF1 and their roles in oncogenesis were also identified through a pan-cancer analysis." (PMID 36421841, 2022). "On the contrary, UPF1 may also play an oncogenic role in cancer by promoting proliferation, migration, invasion, apoptosis and colony-forming ability, as well as have CSC-like characteristics." (PMID 36421841, 2022). "We propose that there might be two main reasons for the inconsistent expression trend of UPF1 in different cancers." (PMID 36421841, 2022). "The dysregulation of UPF1 has been reported in various cancers." (PMID 36421841, 2022). "As a factor of NMD, UPF1 may be involved in many key cellular processes of cancer cells, such as cell differentiation, migration, invasion and cell growth." (PMID 34520393, 2021).
cancer (continued). "Further analysis showed that the mutations did not stop UPF1 from working, in fact, over 40% of these mutations occurred naturally in humans without causing cancer." (PMID 33404013, 2021). "Therefore, a cytotoxic effect on cancer cells was detected in our functional study using siRNA of UPF1 and in previous studies using the overexpression strategy." (PMID 34202873, 2021). "Focusing on the major genes in the NMD pathway (SMG1,5,6,7 and UPF1,2,3B), we first examined whether these genes were amplified in cancer." (PMID 31658270, 2019). "Similarly, in liver cancer, SNHG5 binds to UPF1, an RNA surveillance factor, impairing its function and resulting in the upregulation of Wnt/β-catenin pathway components, which supports stemness and self-renewal of cancer cells." (PMID 41550840, 2026). "UPF1 is dysregulated in multiple human malignancies and may play a role in cancer progression." (PMID 41293174, 2025). "In addition, the effect of cancer-derived mutations in SMG1 (located within 248 aa–910 aa and 2,200 aa–2,400 aa) was characterized, and their effects on the binding affinity and stability in the presence of SMG8, SMG9, and UPF1 were predicted." (PMID 41189592, 2025). "In addition to its involvement in cancer, UPF1 also functions in several other ways." (PMID 35318304, 2022). "However, the mechanism of UPF1 in these cancers needs further study." (PMID 36421841, 2022). "For instance, lncRNA SNHG5 has been found to enhance cancer stem cell-like features and HCC proliferation by modulating UPF1 and the Wnt-signaling pathway." (PMID 38167126, 2024). "In cancers such as microsatellite instability (MSI) cancers, NMD has been shown, on the contrary, to be activated through increased expression of certain NMD-factor genes: UPF1, UPF2, SMG1, SMG6, and SMG7." (PMID 35052820, 2022). "Increasing evidence has shown that UPF1 is significantly downregulated in several cancers, showing that NMD is attenuated to permit oncogenesis; UPF1 downregulation promotes EMT in cancer cells." (PMID 34922601, 2021). "UPF1 is an RNA-dependent helicase and ATPase that is required for NMD of mRNAs containing premature stop codons and takes part in cancer progression." (PMID 34922601, 2021). "Similarly, reduced UPF1 expression in lung adenocarcinoma led to NMD suppression, which activated the TGF-β signaling pathway and contributed to cancer metastasis." (PMID 41293174, 2025). "The upregulation of UPF1 in CRC also leads to chemoresistance in vivo and in vitro to oxaliplatin, a third-generation platinum coordination complex, used for treatment in several types of cancer." (PMID 36766761, 2023). "The present study aims to analyze the effect of SNHG5 on the proliferation and establish the cancer stem cell-like properties of HCC, explore the function of the SNHG5 in regulating the properties of HCC CSCs through UPF1 and Wnt-signaling pathway in vitro, and in promoting tumorigenesis in vivo." (PMID 35338348, 2022). "In cancer cells, Linc-ASEN lncRNA interacts with UPF1 and DCP1A and induces p21 mRNA decay." (PMID 36552825, 2022). "Consistent with this hypothesis, in ARIH1 miniTurboID experiments we detect several interacting proteins with a role in EMT modulation and cancer progression, including TJP1 (ZO1), CYLD, and UPF1." (PMID 35102251, 2022). "This view may be somewhat controversial, as several reports indicate inhibition of NMD in cancer cells, due to inhibition of NMD regulators such as MARVELD1 and UPF1 through promoter hypermethylation." (PMID 34634811, 2021). "As transcription regulation is disrupted in cancer cells, the accumulation of aberrant transcripts has been observed in tumors, detected additionally in such high levels due to the downregulation of the NMD factor, most importantly UPF1, in various cancer types." (PMID 36766761, 2023).
cancer (continued). "Altogether, our work uncovers a novel role for TRIM71 in non-canonical NMD, specifically targeting PTC-lacking mRNAs for NMD/UPF1-mediated decay, and it sheds further light on the RNA recognition and repression mechanisms of this stem cell-/cancer-specific protein." (PMID 31732746, 2019).
infection (20 papers, 2015 to 2025). The state of being infected such as from the introduction of a foreign agent such as serum, vaccine, antigenic substance or organism. "In one of these studies, an siRNA screen revealed that depletion of UPF1 increases the susceptibility of human cell lines to infection with two positive-strand RNA viruses, Semliki Forest virus (SFV) and Sindbis virus." (PMID 25709093, 2015). "The other study employed a genetic screen in Arabidopsis thaliana and found that mutations in the gene encoding UPF1 facilitate infection with Potato virus X (PVX)." (PMID 25709093, 2015). "Prior infection, 293T cells were treated with siRNA against UPF1 or UPF2: the monitoring of p19 by FACS confirmed that the absence of UPF1 provoked the reduction in p19 levels." (PMID 40396490, 2025). "At the onset of the infection, UPF1 leads to a reduction in vRNA and mRNAs levels and fewer cells that are infected, while GSPT1 KD decreased the vRNA level but increased mRNA levels." (PMID 36766761, 2023). "This was prompted by previous reports that indicated that UPF1 translocates between the nucleus and cytoplasm, and our previous observation that UPF1 is selectively downregulated in the nucleus upon infection." (PMID 36603024, 2023). "As expected from these results, UPF1 restricts ZIKV replication—depletion of UPF1 prior to infection resulted in higher viral titers, although features of the viral RNAs that target them for NMD-induced degradation remain to be experimentally defined." (PMID 32699064, 2020). "Accordingly, we have found that UPF1 is degraded following infection of both NPCs and hepatic Huh7 cells." (PMID 30401782, 2018). "Moreover, due to the dataset size, we used a strict cutoff of a log2 fold change of at least 2 to identify the top mRNAs with the most significant decrease in UPF1 interaction upon infection." (PMID 36603024, 2023). "We assessed whether STAU1 expression was affected in SARS-CoV-2 infected Calu3 cells expression and found a peak at 3 h post-infection, thus preceding UPF1 and UPF2 upregulation." (PMID 36768954, 2023). "In later infection, UPF1 and GSPT1 are hijacked, and promote viral replication." (PMID 36766761, 2023). "We speculated that viral RNA could act as a “sponge” sequestering UPF1 away from host RNAs and explaining decreased UPF1 occupancy of host transcripts during infection." (PMID 36603024, 2023). "To test the possibility that MHV mRNAs synthesized early in infection are susceptible to NMD, we inoculated MHV into cells treated with control siRNAs (NMD-competent) or with siRNAs for UPF1 or UPF2 (NMD-deficient) and examined the levels of viral mRNAs at different times p.i.." (PMID 30297408, 2018). "Our data show that NMD inhibition, either by depletion of the NMD factors UPF1 and UPF2 or by wortmannin treatment, resulted in higher levels of MHV mRNA 1 accumulation, which strongly suggests that newly synthesized MHV mRNA 1 is susceptible to NMD early in infection." (PMID 30297408, 2018). "UPF1 co-localized with N and S SARS-CoV-2 proteins, too, and in both cases, the co-localization decreased at 24 vs. 1 h after infection." (PMID 36768954, 2023). "UPF1-mediated RNA decay pathways, such as NMD, SMD and SRD, target viral RNAs yielding a decreased efficiency of infection." (PMID 36766761, 2023). "UPF1 expression was significantly higher at 9 than that at 6 h post-infection, while UPF2 was significantly upregulated at 9 h post-infection compared to that at all the previous timepoints." (PMID 36768954, 2023). "A similar infection restriction by NMD-mediated degradation of viral RNA was observed for Zika virus (ZIKV), using UPF1-depleted human neural progenitor cells (NPCs)." (PMID 36979701, 2023). "We characterized the ubiquitination of the most enriched TRIM25 interactors, G3BP and UPF1, as well as two TRIM25-R54P specific interactors during infection, NME1, and PABPC4." (PMID 36067236, 2022).